INS (insulin)
Diseases named in the same sentence as INS in open-access papers (continued):
Sharing a sentence is not in itself a finding about the gene and the disease.
Insulin resistance (continued). "Himsworth was among the first to show that the mild form was associated with resistance to insulin administration (“insulin resistance”)." (PMID 38299589, 2024). "Obese patients are at risk of insulin resistance, leading to increased insulin secretion to regulate blood glucose levels." (PMID 38741154, 2024). "Cortisol causes insulin resistance and type 2 DM by opposing the anti-gluconeogenic effects of insulin in the liver." (PMID 38339160, 2024). "Recent studies have shown that obesity and insulin resistance are associated with increased insulin-stimulated glucose uptake (GU) in the brain." (PMID 38651416, 2024). "We found that greater UPF consumption was significantly associated with elevated insulin levels and an increased prevalence of insulin resistance." (PMID 39458518, 2024). "Galectin-1 levels were negatively associated with glucose and positively associated with C-peptide levels, fasting insulin, and insulin resistance measured as HOMA and the Matsuda index." (PMID 38777863, 2024). "Aging is associated with progressive impairment of insulin secretion and increased insulin resistance." (PMID 38756148, 2024). "In this situation insulin secretion is inadequate to meet the increased demand caused by insulin resistance." (PMID 39744134, 2024). "Kinases such as IKKβ and JNK can induce the serine phosphorylation of IRS-1, a pivotal component of the insulin signaling pathway associated with insulin sensitivity, leading to insulin resistance and impaired glucose uptake in muscle cells and adipocytes." (PMID 39518420, 2024). "Among them, the decrease in bacterial deconjugation activity of primary bile acids has been frequently observed in MetS, with an increase in fecal levels of cholate and chenodeoxycholate, frequently associated with insulin and insulin resistance in MetS." (PMID 38337675, 2024). "Insufficient levels of vitamin D can cause insulin resistance, which impairs the ability of cells to respond to insulin and worsens the progression of diseases." (PMID 39193371, 2024). "Insulin resistance causes cells to become less responsive to insulin, resulting in higher blood levels." (PMID 38276279, 2024). "We also reported a significant association between FABP4 and increased insulin levels, a marker for insulin resistance." (PMID 38731797, 2024). "Insulin resistance was termed a significant risk factor for the onset of Alzheimer’s disease neuropathology and neurodegeneration, given the crucial function that insulin plays in brain physiology." (PMID 38840158, 2024). "Low vitamin D levels are strongly associated with insulin resistance, impaired insulin secretion, and an increased risk of T2DM cases, especially in people at high risk of T2DM." (PMID 38612580, 2024). "Ectopic lipid accumulation in insulin target tissues is tightly linked to the development of hepatic and systemic insulin resistance." (PMID 39405118, 2024). "Further, due to the close relationship between vitamin D and insulin resistance, we also analyzed the association with insulin-related parameters." (PMID 39408904, 2024). "Outside pregnancy, smoking also increases insulin resistance and has been identified as a modifiable risk factor for impaired insulin secretion, likely mediated by nicotine’s effect on beta-cell function." (PMID 39274361, 2024). "In particular, α-hydroxisobutyrate has been associated with increased insulin resistance and in vitro treatment of pancreatic β-cells with α-hydroxisobutyrate inhibited glucose-mediated insulin secretion." (PMID 37368157, 2024). "Insulin resistance (IR) is a state of responsiveness reduction in insulin-targeting tissues to high physiological insulin levels and considered the pathogenic driver of many diseases, which has become an important public health problem in adolescents." (PMID 38745118, 2024). "Aging is associated with a decline in insulin clearance and insulin resistance, leading to dyslipidemia." (PMID 39408862, 2024).
Insulin resistance (continued). "Testosterone synthesis, regulated by the HPG axis, is reduced in the presence of obesity or dyslipidemia, and this reduction is linked to decreased insulin sensitivity and potential insulin resistance in HPG axis neurons." (PMID 39165513, 2024). "Elevated levels of PAs, especially those containing C16:0 acids, as observed in this study, have been associated with alterations in insulin function and contribute to insulin resistance." (PMID 38932852, 2024). "Although the direct effects of GDF-15 on muscle insulin resistance are not fully understood, elevated GDF-15 levels have been associated with insulin resistance in various tissues, suggesting a potential indirect influence on muscle insulin sensitivity." (PMID 38044678, 2024). "Insulin resistance is associated with the accumulation of free fatty acids, elevated hepatic glucose production and decreased glucose uptake in insulin-sensitive tissues." (PMID 39288128, 2024). "ARHGEF1 plays a significant role in cellular processes such as insulin secretion, insulin signal transduction, and the lipid metabolism, and is associated with type 2 diabetes and insulin resistance." (PMID 39684650, 2024). "It has been shown that aging is associated with an increase in fasting insulin levels, insulin resistance, and central obesity." (PMID 39685728, 2024). "Hyperglycemia eventually results from impaired normal glucose homeostasis caused by either insufficient insulin production or insulin resistance." (PMID 38892571, 2024). "According to the studies conducted on TMAO, this metabolite can cause insulin resistance by blocking the hepatic insulin signaling pathway and also by causing inflammation in adipose tissue in mice, which are themselves one of the components of MetS." (PMID 38321994, 2024). "M1 macrophages are associated with insulin resistance, while anti-inflammatory polarization, M2, is linked to insulin sensitivity." (PMID 38317257, 2024). "Exercise also improves insulin sensitivity, enhancing glucose uptake by muscle cells and reducing the risk of insulin resistance, thereby helping to prevent excessive fat storage." (PMID 39590824, 2024). "The combined therapy led to a significant improvement in obesity-associated insulin resistance (insulin level × FFA level) compared to the control mice." (PMID 39310104, 2024). "Our data indicate that insulin resistance and insulin sensitivity are risk factors for the progression to type 1 diabetes." (PMID 37914981, 2024). "The involvement of the insulin signalling pathway in the regulation of plasticity also highlights a potential role for insulin resistance, which is commonly associated with an increased risk of cancer." (PMID 38778114, 2024). "In the cited study, BMI showed the strongest association with the exanimated indicators — insulin, insulin resistance (HOMA-IR), pancreatic β-cell function (HOMA-β%), and the quantitative insulin sensitivity check index (QUICKI)." (PMID 39897072, 2024). "IL-6 can disrupt insulin signaling and activity, leading to the development of insulin resistance, which is one of the key mechanisms underlying hypertension." (PMID 38515520, 2024). "Mitochondrial dysfunction, such as the loss of function in mitochondria and overproduction of oxidants, plays an important role in the development of impaired insulin metabolic signaling, insulin resistance, and associated diabetic vasculopathy." (PMID 38255878, 2024). "To explore the changes in inflammation levels and insulin resistance caused by platycodin D by reducing intestinal lipid absorption, we detected the expression of inflammatory factors and insulin in the serum of mice fed a high-fat diet." (PMID 39108759, 2024). "MADD is associated with glycemic traits (blood insulin and glucose measurement), which impacts insulin resistance in depressed people, a common risk factor for AD and frailty." (PMID 38706793, 2024).
Insulin resistance (continued). "Type 2 diabetes mellitus (T2DM) is one of the metabolic disorders associated with either β-cell dysfunction or insulin insensitivity in peripheral tissues and is categorized as insulin resistance, which is a main part of metabolic syndromes." (PMID 39329975, 2024). "In conclusion, we demonstrate that glucose tolerance, insulin resistance and insulin sensitivity are associated with retinal layer thicknesses." (PMID 38431705, 2024). "METS-IR, as a novel scoring system for screening insulin sensitivity, can effectively identify individuals at high risk of insulin resistance-associated pathological changes, thus saving costs associated with fasting insulin measurements." (PMID 38987779, 2024). "One example of an insulin resistance-associated gene is AKT which encodes one of the most important protein kinases in the insulin signalling pathway." (PMID 36409629, 2023). "T2D, also known as non-insulin-dependent or adult diabetes, is an age-related disease that refers to hyperglycaemia caused by impaired insulin secretion and insulin resistance." (PMID 37198280, 2023). "Accumulating epidemiological studies suggest that light to moderate alcohol intake is associated with enhanced insulin sensitivity; however, heavy drinking promotes the development of insulin resistance." (PMID 36979389, 2023). "In summary, liver-specific knockout of Zfyve28 in mice significantly improved insulin sensitivity and other relevant indicators associated with insulin resistance." (PMID 37884540, 2023). "Potential explanations for early pathogenic progression of diabetic dysglycemia include genetic predisposition, adiposity-induced insulin resistance, fasting insulin, and beta-cell dysfunction." (PMID 36845048, 2023). "Insulin is known as an important neuromodulator and several studies have observed an association between insulin resistance and both faster rates of cognitive decline and increased risk of memory impairment in older populations." (PMID 37899056, 2023). "Numerous studies have demonstrated that in non-diabetic individuals, the risk alleles of KLF14 genes for T2DM are associated with insulin resistance characterized by increased fasting insulin." (PMID 36837818, 2023). "A reduced intake of saturated fatty acids improves insulin action and is associated with a low risk of insulin resistance and type 2 diabetes." (PMID 37165359, 2023). "It was found that the increase of insulin was associated with the increased risk of EC, indicating that insulin resistance is a potential risk factor of EC." (PMID 37550644, 2023). "In adults with normal glucose tolerance, there is a parallel increase of fasting insulin levels and insulin resistance with aging, and this is associated with central obesity." (PMID 37854186, 2023). "CRP is linked to hepatic insulin resistance through its involvement in impairing insulin signaling in the liver." (PMID 37891561, 2023). "The impaired function of insulin-producing pancreatic β cells in the setting of insulin resistance is the leading underlying cause of type 2 diabetes (T2D)." (PMID 36976988, 2023). "In vitro and ex vivo studies have demonstrated that mitochondrial OxS causes insulin resistance by impairing insulin-regulated GLUT4 translocation to the surface of myotubes (fused skeletal muscle cells) and adipocytes (see Section 3 and Section 4 above)." (PMID 37371869, 2023). "Insulin resistance interferes with glucose removal, causing a compensatory increase in beta-cell insulin production and hyperinsulinemia." (PMID 36904180, 2023). "Proinflammatory cytokines can cause insulin resistance in various target tissues by inhibiting insulin signal transduction, leading to elevated glucose production." (PMID 36767017, 2023). "That is, smoking is believed to promote MS by inducing insulin resistance, reducing insulin sensitivity, and causing hyperglycemia, high blood pressure, hyperinsulinemia, oxidative stress, endothelial dysfunction, and systemic inflammation." (PMID 38288423, 2023).
Insulin resistance (continued). "Compared to WT mice, apoA-IV deficiency displayed glucose intolerance and elevated insulin levels, suggesting insulin resistance." (PMID 37960308, 2023). "Elevated insulin will cause obesity, which in turn leads to insulin resistance—making a continuous cycle until pancreatic beta-cells inadequately meet the insulin demand." (PMID 37092526, 2023). "Serum IL-6 levels were found to be associated with increased BMI, high fasting insulin levels, and insulin resistance in type 2diabetics." (PMID 38250529, 2023). "Insulin resistance is associated with iron overload as insulin can stimulate ferritin synthesis and facilitate iron uptake by cells." (PMID 37768516, 2023). "The findings suggest that the use of statins is associated with a decrease in insulin sensitivity and insulin resistance." (PMID 37465091, 2023). "Prior research demonstrated that BCAAs can inhibit the function of β-cells in regulating insulin secretion; hence, BCAAs are closely associated with insulin resistance and the risk of developing T2DM." (PMID 37755283, 2023). "Across a range of insults causing insulin resistance, we observe a marked rewiring of the insulin signaling network." (PMID 36808134, 2023). "In EA participants we observed NT‐proANP to be inversely associated with insulin resistance and fasting insulin and positively associated with thigh SAT and PMAT." (PMID 36905117, 2023). "High levels of TG and LDL and low levels of HDL are associated with insulin resistance and are independent factors in insulin development." (PMID 37349729, 2023). "Upon such time, mice exhibited worsening of insulin signaling and the activation of gluconeogenic and lipidogenic pathways, suggesting that IL-10 exerts a protective role for liver insulin resistance associated with steatosis." (PMID 37593740, 2023). "Particularly, ceramide and diacylglycerol deposition has been associated with insulin resistance as a result of phosphorylation of essential intermediates in insulin signaling pathways." (PMID 37383391, 2023). "OSA severity is associated with adipose tissue insulin sensitivity and can contribute to the development or worsening of insulin resistance via alteration in FFA metabolism." (PMID 39434962, 2023). "Serum Leptin concentrations demonstrate an association with NAFLD which is mediated through insulin secretory dysfunction and insulin resistance in obese patients." (PMID 37705071, 2023). "Together, these results indicate that whole-body insulin resistance in PpargC/- mice is primarily due to the loss of storage capacity and insulin sensitivity of perigonadal fat." (PMID 36835312, 2023). "Identifying the gut microbiota composition and its association with insulin resistance can help develop strategies that focus on modulating the gut microbiota to promote insulin sensitivity and manage obesity." (PMID 37189387, 2023). "Although hyperglycemia, insulin resistance, and impaired cardiac insulin metabolic signaling are associated with DCM, the pathogenesis of DCM remains complex, and there is no specific treatment to date." (PMID 37009790, 2023). "Both insulin deficiency and insulin resistance lead to decreased brain insulin signaling in PD and contribute to neuroinflammation, mitochondrial dysfunction, and oxidative stress." (PMID 37746149, 2023). "Both involve insulin resistance associated with inadequate insulin secretion and share the same risk factors." (PMID 37869250, 2023). "In contrast, non-Caucasian women were more often multiparous, and showed higher BMI as well as a higher degree of insulin resistance associated with modestly higher HbA1c, fasting glucose and insulin levels." (PMID 38312137, 2023). "The effect of insulin on epigenetics has been illustrated reversely by the case of insulin resistance, which is associated with global DNA hypermethylation." (PMID 36883688, 2023). "The insulin resistance was attributable to an insulin signaling defect that seems to be caused by increased lipid accumulation." (PMID 38001474, 2023).
Insulin resistance (continued). "Another cross-sectional study for children and adolescents also found a significant association between insulin resistance, fasting glucose, and fasting blood insulin with urinary t,t-MA." (PMID 38133386, 2023). "In the clinical setting, increased insulin levels and insulin resistance have been associated with higher areal and volumetric BMD in postmenopausal women, elderly adults and PCOS women." (PMID 37755271, 2023). "Elevated concentrations of C3, an acute-phase response protein, have been shown to be correlated with insulin, glucose, insulin resistance and associated with an increased risk of type 2 diabetes." (PMID 37658860, 2023). "In diabetic dogs, control of hyperglycemia can be established with insulin therapy, diet, exercise, prevention or concomitant control of diseases with insulin antagonism, and the discontinuation of drugs that cause insulin resistance." (PMID 36830471, 2023). "Placental DNA methylation of miR-548 and WWTR1 genes influence insulin sensitivity during pregnancy, and preterm birth and is linked to insulin resistance." (PMID 37434949, 2023). "The rise in the level of GH in serum is considered the most important cause of high insulin requirement and insulin resistance in T1DM patients, being resistant at all stages of puberty." (PMID 37859903, 2023). "Oxidative stress is implicated in the onset of insulin resistance due to the impairment of insulin signaling pathways, as well as in β-cell dysfunction and apoptosis, reducing the number of functional pancreatic β-cells." (PMID 37761009, 2023). "Insulin resistance, obesity, and lipid metabolism disorders are closely related, and the deposition of intracellular lipids can disrupt insulin signaling pathways and abnormal glucose transport and cause insulin resistance." (PMID 37020596, 2023). "T2DM has not an autoimmune trigger but results from the progressive loss of adequate β-cell insulin secretion frequently on the background of insulin resistance." (PMID 37048663, 2023). "The accumulation of liver fat is associated with hepatic insulin resistance (with an impaired ability of insulin to suppress endogenous glucose production), hepatic inflammation and development of peripheral insulin resistance." (PMID 37242149, 2023). "One of the important causes of insulin resistance is the loss of the insulin signaling pathway in the liver, while the IRS-1/PI3K/Akt signaling pathway plays an important role in insulin signaling." (PMID 38201125, 2023). "Insulin resistance, a hallmark of type 2 diabetes, is characterized by an impaired response to insulin and reduced uptake of glucose by the cells." (PMID 37763235, 2023). "Previous studies have demonstrated associations between a wide-range of circulating metabolites and insulin resistance, insulin secretion and type 2 diabetes risk primarily in populations of European ancestry." (PMID 37005925, 2023). "T2D has emerged as one of the leading global health problems and is associated with insufficient insulin secretion from pancreatic β cells and peripheral insulin resistance." (PMID 37762083, 2023). "Because fasting C-peptide can be regulated by the presence of insulin resistance, insulin secretory ability assessment by the disposition index, which takes account of insulin resistance, would be the more suitable method for our analysis." (PMID 37514025, 2023). "Hyperglycemia is associated with insulin resistance, which causes a disorder in glucose uptake into cells through defects in the insulin signal transduction system." (PMID 37432173, 2023). "Obesity-associated insulin resistance was also observed when significantly high insulin levels were required to maintain glycemic control in apoA-IV−/− mice during fasting state and glucose tolerance test." (PMID 37960308, 2023). "Insufficiency of insulin secretion caused by islet β cell dysfunction and insulin resistance (IR) or relative decrease are the leading causes of T2DM." (PMID 37258550, 2023).